SERPINA3 (serpin family A member 3)
Diseases named in the same sentence as SERPINA3 in open-access papers (continued):
Sharing a sentence is not in itself a finding about the gene and the disease.
glioma (continued). "Furthermore, we observed a strong correlation between high levels of SERPINA3, CD68, and IBA1 with reduced survival in patients with primary gliomas." (PMID 41550507, 2026). "Furthermore, we mining related data from the CGGA databases, the results displayed that the levels of SERPINA3 mRNA in WHO III and IV gliomas were higher than that of WHO II." (PMID 41550507, 2026). "While our study provides evidence linking SERPINA3 to glioma malignancy, a key limitation is that the precise mechanistic pathways through which SERPINA3 exerts its pro-tumorigenic effects are not fully elucidated." (PMID 41550507, 2026). "Given that SERPINA3 levels were positively correlated with the expression of CD68 and IBA1 in CGGA databases, suggests that SERPINA3 may involve in forming glioma immunosuppression." (PMID 41550507, 2026). "However, the connection of SERPINA3 level and glioma malignant progression and the GAMs infiltration has not been previously investigated." (PMID 41550507, 2026). "Moreover, we confirmed the co-expression CD68/SERPINA3, IBA1/SERPINA3 in glioma specimens, indicating SERPINA3 may contribute to the intratumoral infiltration of GAMs." (PMID 41550507, 2026). "Moreover, the relation of SERPINA3 levels and CD68, IBA1 was explored in primary gliomas." (PMID 41550507, 2026). "However, SERPINA3 expression in glioma specimens detected by in situ methods has not been previously investigated, and the biological function of SERPINA3 in glioma has not been systematically analysed." (PMID 34449972, 2021). "We have performed a differential expression analysis comparing SERPINA3 and key GAM markers between glioma samples and non-tumor tissues from the databases, which confirmed significant upregulation of SERPINA3 and GAM markers in both LGG and GBM tumors compared to normal tissues." (PMID 41550507, 2026).
melanoma (18 papers, 2013 to 2025). A malignant, usually aggressive tumor composed of atypical, neoplastic melanocytes. "Elevated levels of SERPINA3 are associated with lower survival rates in several malignant melanomas and carcinomas, where the protein is shown to promote cell migration and invasion." (PMID 41270070, 2025). "Our findings suggest that SERPINA3 is involved in or related to the development of invasive behavior in melanoma cells, and thus associated with the progression of melanoma from RGP to VGP." (PMID 27213583, 2017). "In melanoma patients, high SERPINA3 expression was strongly associated with worse overall and disease specific survival at 5 years." (PMID 27213583, 2017). "Our data indicated that up-regulation of SERPINA3 is significantly associated with melanoma progression and worse patient survival." (PMID 27213583, 2017). "SERPINA3 is a protein produced by the liver that has proapoptotic activity and is involved in the process of metastatic invasion in melanoma." (PMID 40299483, 2025). "The highly expressed SERPINA3 (Serpin Family A Member 3) protein is produced by the liver, has proapoptotic activity and is involved in the process of metastatic invasion in melanoma." (PMID 40299483, 2025). "Western blot analysis validated the results observed in the spatial gene expression data, which indicated that co-localized melanoma and primary meningeal cell regions upregulate SERPINA3 when stimulated with co-culture-conditioned CSF." (PMID 38866016, 2024). "Knockdown of SERPINA3 significantly reduced melanoma cell growth and MAPK inhibitor resistance in CSF (p < 0.01 for siRNA1 and p < 0.05 for siRNA2)." (PMID 38866016, 2024). "We now demonstrate that the meningeal stroma is required for melanoma cells to survive in the CSF environment through upregulation of SERPINA3 expression and subsequent activation of the PI3K/AKT and MAPK signaling." (PMID 38866016, 2024). "Elevated SERPINA3 expression was also revealed in cells of primary melanoma as well as its metastasis." (PMID 36672665, 2023). "A previous study found that SERPINA3 promotes the proliferation of melanoma and human liver cancer cells." (PMID 34449972, 2021). "Previous reports showed that SERPINA1 and SERPINA3 are potential prognostic markers and therapeutic targets for colorectal cancer and melanoma, respectively." (PMID 31620367, 2019). "Serpin Peptidase Inhibitor, clade A member 3 (SERPINA3) was found to be abnormally overexpressed in a subset of melanoma tissue biopsies." (PMID 27213583, 2017). "To investigate the expression level of SERPINA3 in the biopsies of pigmented lesions, we performed immunohistochemistry staining of normal nevi, melanoma in situ, primary melanoma and metastatic melanoma cores on TMA slides." (PMID 27213583, 2017). "Cell proliferation was measured using MTS assay by comparing the effect of SERPINA3 siRNA knockdown in MMRU melanoma cells." (PMID 27213583, 2017). "This cell line was derived from a metastatic melanoma and had high intrinsic levels of SERPINA3 expression." (PMID 27213583, 2017). "When SERPINA3 expression was selectively silenced using small interfering RNA molecules (siRNA) in cultured melanoma cell lines, cell migration and matrix invasion was significantly decreased, but no change in cell proliferation was observed." (PMID 27213583, 2017). "In the 366 melanoma cases, we found that high SERPINA3 expression ratio was significantly increased from 45% in AJCC Stage I to 62% in Stage II, and further increased to 74% in Stage III (P = 9.1E-3 and 2.0E-5, respectively, Chi-square test)." (PMID 27213583, 2017). "One hundred and thirty eight melanoma metastases were available for SERPINA3 staining evaluation, including 96 men and 42 women." (PMID 27213583, 2017). "In this study, we set out to test SERPINA3 protein's prognostic potential with a larger-sized and independent patient cohort, and to explore SERPINA3's function in melanoma cells." (PMID 27213583, 2017).
melanoma (continued). "Cox regressions were used to determine the independence of SERPINA3 as a prognostic marker from other factors in melanoma patient survival." (PMID 27213583, 2017). "The interesting finding is that the ability of melanoma cells to invade through Matrigel was severely impaired with down regulation of SERPINA3 expression." (PMID 27213583, 2017). "In this study, we examined the expression pattern of SERPINA3 in a wide spectrum of melanocyte-derived tumor representing the various stages of melanoma progression, including benign nevi, melanoma in situ, invasive primary melanoma, and metastatic melanoma." (PMID 27213583, 2017). "Tissue microarray-based immunohistochemistry analysis showed a significant increase in SERPINA3 expression in invasive and metastatic melanomas compared to normal nevi and melanoma-in-situ (P < 0.001, Chi-square test)." (PMID 27213583, 2017). "This study confirms the prognostic potential of SERPINA3 expression in human cutaneous melanoma and reveals the pro-migration and pro-invasion functions of this protein on melanoma cells." (PMID 27213583, 2017). "To further address this question, we performed in vitro analysis on cultured melanoma cell lines with siRNA-mediated down-regulation of SERPINA3 expression." (PMID 27213583, 2017). "Because of biopsy cores loss and insufficient cells present in some samples, 366 melanomas (228 primary invasive melanomas and 138 metastatic melanomas), 20 melanomas in situ and 25 normal nevi were evaluated for SERPINA3 staining." (PMID 27213583, 2017). "Further testing using Kaplan-Meier confirmed that patients with high SERPINA3 expression have lower survival rates, indicating possible clinical prognostic value of SERPINA3 in melanoma patients." (PMID 27213583, 2017). "In order to determine the prognostic value of SERPINA3, Kaplan-Meier survival tests were run for the 5 year overall survival and disease-specific survival of melanoma patients." (PMID 27213583, 2017). "Cox regression confirmed that SERPINA3 is an independent prognostic marker of patient survival, allowing for more specific prognosis of melanoma patients past the current AJCC system." (PMID 27213583, 2017). "Multivariate Cox regression analysis showed that SERPINA3 expression is an independent prognostic factor to predict melanoma patient clinical outcome." (PMID 27213583, 2017). "Data is presented in this study using all melanoma cases; future studies will strive to clarify SERPINA3's correlation with survival at all stages." (PMID 27213583, 2017). "SERPINA3 knockdown was shown to inhibit the invasion and migration of melanoma cells." (PMID 36672665, 2023). "Furthermore, high expression of Serpina3 was reported in colon and endometrial cancers, and in melanoma." (PMID 33917524, 2021). "Moreover, SERPINA3 is overexpressed in invasive and metastatic melanomas, compared to normal nevi and melanoma-in-situ." (PMID 29513714, 2018). "Knockdown of SERPINA3 declined melanoma migration and invasion abilities." (PMID 29513714, 2018). "It is suggested that SERPINA3 might promote melanoma invasion through remodeling the extracellular tissue matrix." (PMID 27213583, 2017). "A significant increase of SERPINA3 expression in melanomas thicker than 2 mm compared to that in thinner tumors was also detected (P = 8.5E-3, Chi-square test), which is further evidence that SERPINA3 could be important in melanoma progression." (PMID 27213583, 2017). "An early report revealed that the serum of SCID (Severe Combined Immunodeficient) mice carrying human metastatic melanoma cell lines had increased levels of SERPINA3; SERPINA3 also presented in 10 out of 17 melanoma biopsies within a large cancer pathology series." (PMID 27213583, 2017). "SERPINA3 expression levels appear to strongly correlate with melanoma invasion and metastasis." (PMID 27213583, 2017).
melanoma (continued). "Preliminary analysis on 216 patient tissue samples by our group showed that melanoma patients with high expression of SERPINA3 have shorter disease specific survival, suggesting that SERPINA3 expression could serve as a prognostic marker in melanoma." (PMID 27213583, 2017). "This study demonstrated that the up-regulation of SERPINA3 in advanced melanoma may contribute to the invasive behavior of melanoma cells by remodeling the extracellular tissue matrix." (PMID 27213583, 2017). "In-vitro cell-based assays demonstrated enhanced cell migration and invasion by high SERPINA3 expression, suggesting that SERPINA3 may play an important role in melanoma progression." (PMID 27213583, 2017). "SERPINA3 is involved in promoting the invasion and metastasis of malignant melanomas and cell lines, where it may have a role in regulating apoptosis and invasiveness." (PMID 24179540, 2013). "In addition, SERPINA3 was shown to promote migration and invasion of melanoma cells." (PMID 32602849, 2020). "Therefore, molecules targeting SERPINA3 or maybe other serpins may have therapeutic implications for melanoma in the near future, although the precise mechanism of how SERPINA3, the serine protease inhibitor, affects the structure of ECM remains to be elucidated." (PMID 27213583, 2017). "Interestingly, STAT3 is one of the transcription factors responsible for the increase in SERPINA3 gene expression after the stimulation of the integrin–FAK–AKT signaling pathway, which leads to the migration of melanoma cells." (PMID 36672665, 2023). "This is consistent with the findings that SERPINA3 expression is largely absent in tissues of melanoma in situ, in which the melanocytes have already acquired their malignant proliferating properties." (PMID 27213583, 2017). "Not surprisingly, higher SERPINA3 expression (65%) was found in ulcerated melanomas compared to that in ulceration absent tumors (46%) (P = 0.0378, Chi-square test)." (PMID 27213583, 2017). "Not surprisingly, down-regulation of SERPINA3 expression did not demonstrate an effect on the proliferation, survival and attachment of the melanoma cells (data not shown)." (PMID 27213583, 2017). "The dramatic increase of SERPINA3 expression during the transition from benign or non-invasive lesions to invasive and metastatic tumors suggests that SERPINA3 is potentially involved in the development of invasiveness in advanced stages of melanoma." (PMID 27213583, 2017). "While SERPINA3 may not be acting directly to induce this effect, knockdown of SERPINA3 is sufficient to decrease melanoma migration and invasion abilities." (PMID 27213583, 2017). "Therefore, it is possible that the SERPINA3 findings from this cohort may not represent the biology of all melanoma patients with LMD." (PMID 38866016, 2024).
heart failure (17 papers, 2018 to 2025). Inability of the heart to pump blood at an adequate rate to meet tissue metabolic requirements. "Elevated levels of SERPINA3 (encoded by the SerpinA3 gene) have been observed in heart failure and neurological diseases." (PMID 39062058, 2024). "Beyond its myocardial expression, elevated circulating levels of SERPINA3 have been linked to an increased cancer risk in heart failure patients, highlighting the necessity for more in-depth exploration of its clinical implications and molecular functions." (PMID 39717447, 2024). "Experimental studies have demonstrated that heart failure may increase the risk of developing tumors by releasing specific heart failure-related proteins, like SERPINA3, into the bloodstream." (PMID 39062777, 2024). "SERPINA3 is expressed in failing hearts and has been described as a prognostic marker for both de novo and worsening heart failure with reduced ejection fraction." (PMID 40087712, 2025). "By intersecting the findings from all three algorithms, we pinpointed four diagnostic genes for the pre-decompensation stage of heart failure: SMOC2, OGN, FCN3, and SERPINA3." (PMID 39717447, 2024). "A study in a MI-induced heart failure (HF) mouse demonstrated an increase in cardiac expression of SerpinA3, resulting in an enhanced proliferation of colon cancer cells." (PMID 38279150, 2024). "SERPINA3 recently emerged as potential prognostic biomarker in heart failure." (PMID 40087712, 2025). "An animal experimental study revealed that heart failure resulting from AMI can promote the growth of intestinal tumors in mice, which may be associated with some secreted cardiac proteins—particularly SerpinA3." (PMID 40926981, 2025). "Clinical evidence suggests that heightened SERPINA3 levels in individuals with new-onset or exacerbating heart failure correlate with increased mortality rates or unplanned cardiac readmissions, underscoring its prognostic value for heart failure." (PMID 39717447, 2024). "However, a recent study found that SERPINA3 expression was decreased in heart failure patients compared with control subjects, indicating that SERPINA3 played a protective role during the process of heart failure." (PMID 36863704, 2023). "The results suggest that the determination of the level of SERPINA3 gene expression could be used to prevent and monitor the treatment of heart failure after myocardial infarction." (PMID 36672665, 2023). "SERPINA3 is significantly perturbed in heart failure proteins shared between two studies." (PMID 38077583, 2023). "SERPINA3 may be as well utilized as a heart failure predictive biomarker with great potential." (PMID 36148059, 2022). "Using existing gene expression data in the Gene Expression Omnibus (GEO) database, we screened differentially expressed genes (DEGs) of heart failure and identified six key genes (HMOX2, SERPINA3, LCN6, CSDC2, FREM1, and ZMAT1) by random forest classifier." (PMID 33401250, 2020). "This confirms a previous report on a negative correlation of HDL with SERPINA3 in a heart failure population." (PMID 40087712, 2025). "SERPINA3 at three months additionally was significantly correlated with hs-cTnI and GLS directly after the end of AnC, which is in line with previous studies in patients with heart failure and CTRCD." (PMID 40087712, 2025). "We screened for differentially expressed genes in heart failure using available gene expression data from the Gene Expression Omnibus database and identified 6 important genes by a random forest classifier (ASPN, MXRA5, LUM, GLUL, CNN1, and SERPINA3)." (PMID 36254001, 2022).
colon carcinoma (13 papers, 2019 to 2025). "Increased SerpinA3 expression in colon cancer tissues was associated with higher metastasis." (PMID 38279150, 2024). "In an MI mouse model which showed enhanced tumor growth, the SerpinA3 expression was increased in cardiac tissue, and an in vitro study demonstrated its role in increasing the growth of colon cancer cells." (PMID 38279150, 2024). "In mice injected with downregulated SerpinA3 colon cancer cells, a decrease in liver metastasis was demonstrated." (PMID 38279150, 2024). "SerpinA3 expression was increased in various cancer cell lines including colon cancer and lung adenocarcinoma cell lines." (PMID 38279150, 2024). "Serpina3 stimulates the proliferation of colon tumor cells in vitro via an Akt (also known as protein kinase B)-dependent pathway, a signal transduction pathway that promotes survival and growth in response to extracellular signals." (PMID 38203612, 2023). "They found that cardiac expression of Serpina3 was increased in the mice and that SerpinA3 protein promoted proliferation of HT-29 colon cancer cells." (PMID 32411724, 2020). "SerpinA3 also promoted the proliferation of colon cancer cells after in vitro exposure." (PMID 38279150, 2024). "In vitro stimulation of the human colon cancer cell line HT29 identified SerpinA3 as a driver of cancer cell proliferation via AKT pathway activation, highlighting the protein SerpinA3, which is released from failing hearts, as a potential driver of colon cancer tumorigenesis." (PMID 39340596, 2024). "SERPINA3 silencing effects in two colon cancer cell lines were investigated." (PMID 38087342, 2023). "It is also known that IHC staining for SERPINA3 is higher in colon cancer tissue compared to normal tissue; moreover, SERPINA3 silencing by siRNA reduces the level of migration, invasion, metastases, and the expression of metalloproteinase in in vitro and mice models of colorectal cancer (CRC)." (PMID 33266496, 2020).
colorectal cancer (13 papers, 2019 to 2025). A primary or metastatic malignant neoplasm that affects the colon or rectum. "Studies have shown that serpinA3 protein is upregulated in patients with heart failure as well as in APCmin mice, a line that is prone to colorectal cancer, in which infarction was induced." (PMID 39634266, 2024). "Additionally, SERPINA3 has also been described as a circulatory biomarker for colorectal cancer and prostate cancer." (PMID 40087712, 2025). "Changes in CDX gene expression further promoted metastasis as ICAM-1 increases cancer cell invasion/intravasation into the microvasculature and mediates peritoneal carcinomatosis HP promotes colorectal cancer cell motility and SERPINA3 promotes tumor cell migration and invasion." (PMID 34010296, 2021). "Additionally, the levels of periostin, connective tissue growth factor (CTGF), and plasma cuprocyanin, all of which have significant roles in cancer progression, were elevated in these mice, as was that of serpinA3 protein, which promotes colorectal cancer development." (PMID 39634266, 2024). "Additionally, serpinA3 upregulation resulted in increased phosphorylation of both AKT and its downstream target ribosomal protein S6 (rpS6), which contributed to colorectal cancer development." (PMID 39634266, 2024).